GATA4 (GATA binding protein 4)
Diseases named in the same sentence as GATA4 in open-access papers (continued):
Sharing a sentence is not in itself a finding about the gene and the disease.
bladder cancers (1 paper, 2016). "All these data indicated GATA4 and ETS1 played essential roles in the drug resistance of MLL mutated bladder cancer cells." (PMID 26625313, 2016). "In this paper, MLL particularly altered in recurrent bladder cancers with elevated modification of H3K4me3 and increased expression of GATA4 and ETS1 downstream." (PMID 26625313, 2016). "Taken together, MLL mutation, elevated GATA4 and EST1 would be the promising biomarkers for diagnosis and targets for treatment of bladder cancer recrudescence." (PMID 26625313, 2016). "Specifically, the recurrent BCs and bladder cancer cells with MLL mutation displayed increased histone H3 tri-methyl K4 (H3K4me3) modification in tissue and cell levels and showed enhanced expression of GATA4 and ETS1 downstream." (PMID 26625313, 2016). "Moreover, GATA4 and ETS1 played an indispensable role in the drug-resistance of bladder cancer cells with MLL mutation." (PMID 26625313, 2016). "Thus, MLL mutation, GATA4 and ETS1 may be used as a the biomarkers for diagnosis and targets for treatment of bladder cancer recrudescence." (PMID 26625313, 2016). "In this study, we introduced the MLL mutation into bladder cancer transitional cell line T24 and confirmed that the mutation didn't influence the expression of MLL but increased the H3K4me3 modification in GATA4 and ETS1 promoters and the expression levels of GATA4 and ETS1." (PMID 26625313, 2016). "The increased modification of H3K4me3 and expression of GATA4 and ETS1 would be the promising targets for the diagnosis and therapy of relapsed bladder cancer." (PMID 26625313, 2016). "Furthermore, the enhanced expression of GATA4 and ETS1 indeed contributed to the drug-resistance of bladder cancer cells." (PMID 26625313, 2016). "The elevated expression of GATA4 and ETS1 negatively correlated with the prognosis of bladder cancer patients and may be involved in bladder cancer relapse." (PMID 26625313, 2016). "However, the relationship between GATA4 and bladder cancer have not been reported so far." (PMID 26625313, 2016).
bladder tumor (1 paper, 2016). "Taken together, GATA4 and ETS1 overexpression mediated by MLL mutation enhanced the ability of drug-resistant to epirubicin which endowed mutated bladder tumor cells the advantage of survival and recurrence in the presence of chemotherapeutics." (PMID 26625313, 2016).
Bochdalek's hernia (1 paper, 2016). "In summary, Bochdalek's hernia could be regarded as an atavistic condition related with the failure in the ontogenetic/evolutionary process which replaced the thoracic intermediate mesoderm by lateral plate mesoderm expressing GATA4 under control of the G2 enhancer." (PMID 27642710, 2016).
breast tumors (1 paper, 2021). "While no direct tumor suppressive functions of GATA4 have been identified, it has been shown that restoration and even overexpression of GATA4 can impede the progression of breast tumors." (PMID 33778495, 2021).
celiac disease (1 paper, 2016). An autoimmune genetic disorder with an unknown pattern of inheritance that primarily affects the digestive tract. "Upon our analyses, Gata4 deleted mice did not display classical signs of celiac disease associated signature, such as for instance, modification in the expression of IL-15 or activating natural killer receptor NKG2D gene transcripts (data not shown)." (PMID 27827449, 2016).
cervical squamous cell carcinoma (1 paper, 2021). A squamous cell carcinoma arising from the cervical epithelium. "13.8% of 297 cervical squamous cell carcinoma cases revealed that genetic alterations in the five-gene signature with a low frequency of ALDH1A2 (1.3%), OSR2 (1%), GRIA4 (4%), GATA4 (1%), and IRX4 (7%)." (PMID 34745985, 2021).
Chagas disease (1 paper, 2017). A parasitic infection caused by Trypanosoma cruzi. "Some of these differentially expressed genes were previously associated to Chagas disease (eg, IL7, CCR7, CCL19, GATA4, HLA-DPB1)." (PMID 28575239, 2017).
channelopathy (1 paper, 2024). Channelopathies are a group of diseases caused by the dysfunction of ion channel subunits or their interacting proteins. "The variants included three channelopathy-associated genes (RYR2, CACNA1C, and ANK2), three HCM- or DCM-associated genes (MYH7, LDB3, and PRKAG2), five ACM-related genes (PKP2, JUP, DSG2, DSP, and TMEM43), and two cardiac transcription factor genes (TBX5 and GATA4)." (PMID 39272661, 2024).
clear cell carcinomas (1 paper, 2009). "Among the informative cases, loss of GATA4 was found in 81/82 (99%) of serous carcinomas, 1/12 (8.3%) of mucinous carcinomas, 11/12 (92%) of clear cell carcinomas, and 5/5 (100%) of endometroid carcinomas." (PMID 19649254, 2009).
co-infection (1 paper, 2021). "This anti-senescent effect was reversed by the co-infection with miR-199a-3p mimic and Ad-GATA4." (PMID 34864645, 2021).
colon adenocarcinoma (1 paper, 2021). "Through Kaplan-Meier analysis of colon adenocarcinoma in TCGA database, it was revealed that a higher GATA4 expression is associated poorer prognosis in CRC males, but not in females." (PMID 34987705, 2021).
COVID-19 (1 paper, 2024). A disease caused by infection with severe acute respiratory syndrome coronavirus 2. "GATA-4 was reduced in our COVID-19 patients, indicating that subsequent remodelling pathways may be impaired." (PMID 38760690, 2024).
diffuse large B-cell lymphoma (1 paper, 2015). "In diffuse large B-cell lymphoma (DLBCL) GATA4 showed significant methylation in over 85 % of tumors." (PMID 26490736, 2015).
Down syndrome (1 paper, 2020). "Genetic defects of Nkx 2–5, GATA4, Tbx5 and Downs syndrome are known to be linked with ASD pathogenesis." (PMID 33250054, 2020).
dysgerminoma (1 paper, 2023). A malignant germ cell tumor characterized by the presence of a monotonous primitive germ cell population. "Interestingly, GATA-4 expression was stronger in high-stage dysgerminomas as compared to low stage." (PMID 37372675, 2023). "For example, all of the YST strongly expressed GATA-4, GATA-6, and HNF-4, while dysgerminomas partly expressed GATA-4 (five out of eight), though they did not express GATA-6 or HNF-4." (PMID 37372675, 2023).
dyslipidaemia (1 paper, 2013). "One of the potential culprits at this locus is GATA4, which we elected to pursue further for its role in dyslipidaemia-related onset of CAD." (PMID 24330461, 2013). "Since the outgoing notion was that GATA4 may mediate dyslipidaemia-mediated onset of CAD, it was interesting to investigate whether haplotyping might reveal any link with lipidaemic disorders." (PMID 24330461, 2013). "Hence, the novel finding implicating the GATA4 in dyslipidaemia seems to point to yet undefined entities, possibly involving the regulation of the GATA4 functional state, as playing an important role in the disease process." (PMID 24330461, 2013).
endometrial cancer (1 paper, 2013). Primary or metastatic malignant neoplasm involving the endometrium (mucous membrane that lines the endometrial cavity). "All EpiMods demonstrated strong enrichment for biological terms, with the HAND2 EpiMod itself highly enriched for other transcription factors (e.g., GATA4, HEY2, HOXD13, PHOX2A, HAND1), all of which were also hypermethylated in endometrial cancer." (PMID 24265601, 2013). "All these results indicate that HAND2 and the interaction neighbourhood of HAND2, including GATA4, HEYL, and PHOX2A, represent a core component that is epigenetically deregulated in endometrial cancer." (PMID 24265601, 2013).
endometrioid ovarian cancer (1 paper, 2009). "GATA4 and GATA6 were found to be absent in high percentages (80 to 90%) of serous, clear cell, and endometrioid ovarian cancer examined." (PMID 19649254, 2009).
enteritis (1 paper, 2016). Inflammation of the small intestine. "Administration of indomethacin, a non-steroidal anti-inflammatory drug (NSAID) that causes enteritis, led to rapid and restricted proximal small intestinal injuries in Gata4 mutant mice as opposed to control mice." (PMID 27827449, 2016).
esophageal cancer (1 paper, 2025). A primary or metastatic malignant neoplasm involving the esophagus. "Lastly, esophageal cancer often exhibits intrachromosomal amplification of MYC, ERBB2, EGFR, RB1, GATA4/6, CCND1, RTK and MDM2 as well as ecDNA-associated amplification of MYC and MDM2." (PMID 41415205, 2025).
female infertility (1 paper, 2024). Diminished or absent ability of a female to achieve conception. "In vitro studies point to a role of GATA4 in ovarian steroidogenesis by impairing estradiol synthesis, and conditional knockdown of Gata4 in mice showed female infertility." (PMID 39391877, 2024).
fibroma (1 paper, 2012). A non-metastasizing neoplasm arising from the fibrous tissue. "In fibroma/thecoma group GATA-4 and FOG-2 point out the abnormal activation of GATA pathway and might be involved in the onset of these tumors." (PMID 23029311, 2012). "GATA-4 and FOG-2 were detected in fibroma and thecoma but not in the SST." (PMID 23029311, 2012).
folate deficiency (1 paper, 2019). A nutritional condition produced by a deficiency of FOLIC ACID in the diet. "Using ChIP-seq and RNA-seq assays, we demonstrated that an increase in H2AK119ub1 level downregulated the expression of the NTC-related genes Cdx2, Nes, Pax6, and Gata4 in mESCs under conditions of folate deficiency." (PMID 31722724, 2019).
Gastric Metaplasia (1 paper, 2008). Intestinal metaplasia of the gastric mucosa is an intermediate precancerous gastric lesion in the gastric cancer cascade from chronic gastritis and atrophy to dysplasia and adenocarcinoma. "Furthermore, TFF and mucin proteins have been shown to be present in esophageal and gastric metaplasias, similarly to GATA-4 and GATA-6 (this study)." (PMID 18405344, 2008).
gastric tumors (1 paper, 2024). "Given the marked presence of GATA4 and 6 in gastric tumors, a collection of publicly available ChIP-seq data (see M&M) was used in order to molecularly dissect their regulatory role in the disease, focusing on their chromatin interactions in GC cells." (PMID 39456519, 2024). "We also observed a statistically significant inverse correlation between high levels of GATA4 or 6 and invasion-free probability in gastric tumors." (PMID 39456519, 2024). "In addition, the GATA4 and 6 loci have been shown to undergo genomic amplification in gastric tumors, which further highlights their oncogenic role in these tumors and aligns well with the observed upregulated levels of both factors in our patient sample analysis." (PMID 39456519, 2024).
germ cell tumor (1 paper, 2012). A benign or malignant, gonadal or extragonadal neoplasm that originates from germ cells. "GATA-4 is also expressed in sex cord-derived tumors and adult germ cell tumors and it has been observed that its high expression is associated with a more aggressive behaviour, therefore it represents a useful marker of poor prognosis." (PMID 23029311, 2012). "In the group of germ cell tumors of children and young adults, GATA-4 and GATA-6 are expressed in yolk sac tumors but not in mature teratomas." (PMID 23029311, 2012).
gestational hypertension (1 paper, 2023). "They used a mouse model to demonstrate that gestational hypertension could lead to increases in LV Gata4, Gate 6 and P300 in offspring and remodeling of the fetal left ventricular structure and could finally result in fetal diastolic dysfunction." (PMID 37685293, 2023).
gonadoblastoma (1 paper, 2018). A mixed germ cell/sex cord-stromal tumor characterized by the presence of large germ cells which resemble seminoma cells and small cells which resemble Sertoli or granulosa cells. "Risk of gonadoblastoma is high when the early stage of Sertoli cell differentiation is disrupted by mutations in SRY, WT1, SOX9, DMRT1, FOG2/GATA4, FGF9 etc.." (PMID 28825592, 2018).
hypertriglyceridemia (1 paper, 2022). A laboratory test result indicating elevated triglyceride concentration in the blood. "Given that knockout of Apoa5 in mice increases plasma TG level, and mutation at APOA5 gene causes hypertriglyceridemia and elevated TC19,22, GATA4 may affect TG and TC homeostasis through APOA5." (PMID 35046404, 2022).
idiopathic thrombocytopenic purpura (1 paper, 2015). "GATA4 transcript levels were significantly decreased in AML patients (33.06 ± 70.94; P = 0.011) compared to normal bone marrow/idiopathic thrombocytopenic purpura controls (116.76 ± 105.39)." (PMID 26490736, 2015).
intestinal cancer (1 paper, 2022). "We previously reported that Mll1 regulates the expression of the transcription factor Gata4 to sustain stemness and restrict secretory goblet cell differentiation of β-catGOF intestinal cancer stem cells." (PMID 35064075, 2022).
intestinal tumor (1 paper, 2020). "Transcriptome profiling of Wnt-mutated intestinal tumor-initiating cells reveals that Mll1 regulates Gata4/6 transcription factors, known to sustain cancer stemness and to control goblet cell differentiation." (PMID 33349639, 2020).
ischemic cardiomyopathy (1 paper, 2021). Ischemic cardiomyopathy is a cardiomyopathy in which a weakness in the muscle of the heart due to inadequate oxygen delivery to the myocardium with coronary artery disease being the most common cause. "Consequently, GATA4 has emerged as a promising therapeutic target for ischemic cardiomyopathy." (PMID 33578393, 2021).
liposarcoma (1 paper, 2025). A usually painless malignant tumor that arises from adipose tissue. "This study aimed to investigate the gene expression profiles of SOX9, GATA3, and GATA4 in liposarcoma subtypes and to assess their associations with clinicopathological parameters." (PMID 41303462, 2025). "Notably, although SOX9, GATA3, and GATA4 have been previously implicated in various malignancies, this is the first qRT-PCR-based study to systematically quantify their expression in human liposarcoma tissue." (PMID 41303462, 2025). "The relative expression values (RQ) of SOX9, GATA3, and GATA4 were evaluated in 42 liposarcoma cases." (PMID 41303462, 2025). "Boxplot analysis confirmed substantial interindividual variability in the expression levels of SOX9, GATA3, and GATA4 across the 42 analyzed liposarcoma cases." (PMID 41303462, 2025). "Overall, the heterogeneous expression profile of GATA4 supports its potential involvement in diverse transcriptional programs relevant to liposarcoma pathogenesis." (PMID 41303462, 2025). "Despite progress in molecular diagnostic tools, the current literature offers limited data regarding the expression profiles of transcription factors such as the Sex-determining region Y-box 9 (SOX9), GATA3, and GATA4 in liposarcoma." (PMID 41303462, 2025). "Considering these knowledge limitations, the present study aims to evaluate the relative expression levels (RQ) of SOX9, GATA3, and GATA4 in a series of human liposarcoma samples, using a comparative molecular approach based on quantitative real-time PCR." (PMID 41303462, 2025). "This study provides qRT-PCR-based evaluation of SOX9, GATA3, and GATA4 gene expression in liposarcomas, revealing consistent overexpression patterns across multiple histological subtypes." (PMID 41303462, 2025). "In this study, we conducted a comprehensive molecular analysis of SOX9, GATA3, and GATA4 gene expression in a cohort of 42 liposarcoma cases using quantitative real-time PCR." (PMID 41303462, 2025). "To assess the prognostic relevance of SOX9, GATA3, and GATA4 gene expression levels on overall survival in liposarcoma patients, we performed univariate Cox proportional hazards regression using continuous RQ values as covariates." (PMID 41303462, 2025). "Collectively, these findings underscore that the altered expression of SOX9, GATA3, and GATA4 observed in liposarcoma may reflect dysregulated MSC differentiation mechanisms and impaired adipogenic transcriptional control." (PMID 41303462, 2025). "While exploratory, this shared miRNA regulatory signature suggests that GATA3 and GATA4 may participate in a coordinated transcriptional module in liposarcoma." (PMID 41303462, 2025). "Together, these data justify investigating SOX9, GATA3, and GATA4 within the mesenchymal context of liposarcoma, where they may cooperatively contribute to aberrant lineage maintenance and tumor progression." (PMID 41303462, 2025). "Collectively, these observations raise the hypothesis that GATA3 and GATA4 act in parallel or complementary fashion to support phenotypic adaptability or dedifferentiation programs in liposarcoma." (PMID 41303462, 2025). "This raises the possibility that SOX9, GATA3, and GATA4 are not merely subtype-specific markers but may instead reflect a broader oncogenic pathway active across diverse liposarcoma variants." (PMID 41303462, 2025). "An important and somewhat counterintuitive observation in our dataset was the frequent overexpression of SOX9 and GATA4 in ALT/WDLS cases, which are classically regarded as low-grade or well-differentiated liposarcoma subtypes." (PMID 41303462, 2025).
liver cirrhosis (1 paper, 2024). "Given that GDF2 and BMP10 regulated the expression of Gata4 in murine ECs, it is possible that the reduced expression of GATA4 may be due to low expression of GDF2 and BMP10 in liver cirrhosis." (PMID 39453386, 2024).
lupus (1 paper, 2024). "This suggested that GATA4 is involved in lupus pathogenesis." (PMID 38605949, 2024). "Because our RNA-seq data were generated from STING-activated monocytes, we asked whether GATA4 was constitutively upregulated in lupus monocytes." (PMID 38605949, 2024).
lymph node metastasis (1 paper, 2023). "However, when we investigated the differences between tumor tissue and lymph node metastasis, we found that while GATA4 expression remained stable in 71% of the cases, loss of GATA6 expression was common, being detected in up to 40% of cases." (PMID 36830789, 2023).
mesenchymal tumors (1 paper, 2025). "In contrast to GATA2, which primarily acts as an upstream repressor of adipogenesis, GATA3 and GATA4 are dynamically modulated during differentiation and have been implicated in the transcriptional plasticity of mesenchymal tumors." (PMID 41303462, 2025).
microstomia (1 paper, 2020). "Moreover, the microdeletion of BARX1 in humans is associated with craniofacial developmental disorders such as microstomia and mandibular retrusion, while BARX1 was recently shown to function as a direct downstream factor of GATA4 in neural crest development." (PMID 32571211, 2020).
migraine (1 paper, 2008). "This study aimed to determine the role of the S377G polymorphism in the GATA-4 gene in migraine and if there is a significant association between patients with migraine and this mutation." (PMID 19018306, 2008). "Further studies investigating other GATA-4 variants in families and case/control populations are warranted to more clearly determine whether this gene plays a role in migraine." (PMID 19018306, 2008).
mucinous carcinoma (1 paper, 2009). "Thus, the expression of GATA4 and GATA6 distinguishes mucinous carcinomas from other histological subtypes." (PMID 19649254, 2009).
muscular disease (1 paper, 2017). Myopathy is a peripheral nervous system disease consisting of any abnormal condition or disease of the muscular tissues; commonly designates a disorder involving skeletal muscle. "Tcf4-positive CT cells also express Gata4, known to be mutated in CDH, and Gata4 inactivation in diaphragm CT leads to hernias similar to those observed in CDH, demonstrating that this congenital muscular disease is related to a defect in muscle irregular CT." (PMID 28386539, 2017).